CRP (C-reactive protein)
Diseases named in the same sentence as CRP in open-access papers (continued):
Sharing a sentence is not in itself a finding about the gene and the disease.
COVID-19 (continued). "We found that CRP correlated with IL-6 in either COVID-19 or non-COVID-19 patients (rs = 0.65, p < 0.001 and rs = 0.72, p < 0.001, respectively), and that NP correlated with CRP in non-COVID-19 patients (rs = 0.618, p = 0.00217)." (PMID 35529699, 2022). "Numerous clinical and laboratory scores that include C-reactive protein (CRP), D-dimer, ferritin, lactate dehydrogenase (LDH), interleukin 6 (IL-6), procalcitonin (PCT), blood urea nitrogen (BUN), creatinine levels and oxygenation (PaO2 and SaO2) have been used for the prognosis of COVID-19." (PMID 35935801, 2022). "Although an important amount of data indicates a strong association between COVID-19 evolution and CRP, D-dimer, ESR, procalcitonin, ferritin concentrations, etc., it should be taken into account that these findings are related to COVID-19 patients in general, regardless of the disease severity." (PMID 35743751, 2022). "In addition, COVID-19 patients who have increased levels of CRP need constant monitoring and therapy even if they did not acquire symptoms that fit the criteria for the severe disease course." (PMID 36431254, 2022). "At the time of discharge the laboratory results revealed that the patients with statins showed a lower mean of WBC count (7.6 × 103/μL vs. 8.1 × 103/μL, p < 0.01), and C-reactive protein (100 mg/L vs. 120.7 mg/L, p < 0.001) compared to non-statin COVID-19 patients." (PMID 35865966, 2022). "In the present study, we measured the levels of NP, CRP, and IL-6 in patients suffering from COVID-19 and those with noninfectious respiratory symptoms and compared their correlations to examine whether these values would reflect similar biological processes." (PMID 35529699, 2022). "We hypothesize that the pro-inflammatory effect of Lp(a) on endothelial cells in COVID-19 patients may be local and connected with atherogenesis, and therefore may not be manifested in CRP or IL-6 serum concentration." (PMID 35675355, 2022). "However, levels of C-reactive protein (CRP) were elevated in five out of six animals from day 1 post-challenge compared to pre-challenge baseline levels, but these levels were below diagnostically significant levels described in human COVID-19 cases." (PMID 35891560, 2022). "Laboratory tests (CRP, LDH) might not have accurately reflected the COVID-19 associated inflammatory response due to the presence of some other comorbid condition." (PMID 35217881, 2022). "Thus, we aimed to monitor its methylation status and its impact on the response elements within HeyL promoter in COVID-19 patients and, in addition to, study its correlation with the clinical outcomes and the routine biomarkers including PLR, CRP, ferritin and D-dimer." (PMID 35655915, 2022). "Cytokines, PCT and CRP in ICU vs. non-ICU patients with COVID-19." (PMID 35500008, 2022). "In summary, the present findings provide further support for using SDC-1 alone or combined with other markers such as IL-6, TNF-α, CRP, PCT, and D-dimer as possible indicators for predicting severity and could be a valuable approach for monitoring the disease activity of COVID-19." (PMID 36556051, 2022). "Similarly, since dexamethasone is only recommended for the most severe patients with COVID-19, patients with dexamethasone had higher CRP (158.8 mg/L; SD = 114.9 mg/L) than those not on Dexamethasone (102.8 mg/L; SD = 90/8 mg/L) (p < 0.001)." (PMID 35646997, 2022). "At variance, our data were obtained only in hospitalized COVID-19 patients, in whom a panel of biomarkers were compared with NLR, thereby emphasizing its prominent prognostic role, as well as both the pattern of its increase over time compared with CRP and the inverse relationship with P/F." (PMID 35456328, 2022).
COVID-19 (continued). "Compared to COVID-19 patients, influenza pneumonia patients had higher temperatures (p < 0.001), WBC counts (p < 0.001), neutrophil counts (p < 0.001), neutrophil rates (p = 0.017), and CRP levels (p = 0.033), and lower lymphocyte rates (p = 0.005), which were also confirmed by multiple tests." (PMID 35602019, 2022). "Dissecting the direct (non-mediated) effect of CUD on COVID-19 adverse outcomes from the total effect requires a comprehensive assessment of the plausible mediator trait(s) (e.g., CRP) and availability of sufficiently powered GWAS, which is beyond the scope of our analysis." (PMID 36583016, 2022). "Similarly, CRP and LDH levels account for the intensity of systemic inflammation and tissue damage, respectively, and are known to correlate with critical illness and death in COVID-19 patients." (PMID 35337049, 2022). "Hence, it seems that infection, rather than SPS, drives the elevation of CRP in severe COVID-19, although it should be noted that the maximal level of CRP recorded during the entire ICU stay was not sampled at a standardized time point." (PMID 36555328, 2022). "CRP was found specifically to be positively correlated with two parts of a Continuous Performance Test (CPT) conducted in patients who had resolved COVID-19 infections and was found at significantly elevated concentration in COVID-19 patients with moderate to severe cognitive dysfunction." (PMID 36268187, 2022). "Other independent predictors for 30-day mortality in COVID-19 patients included age, male sex, viral load, cardiovascular accident (CVA), chronic obstructive airway disease (COAD), arrhythmia, low hemoglobin, low eGFR, hypoalbuminemia, white cell count, CRP, and D-dimer levels (P < 0.05, for all)." (PMID 36714113, 2022). "The NEWS score was a better risk indicator than qSOFA, considering parameters that are known to increase in severe COVID-19, including levels of total leukocytes, neutrophils, plasma CRP, and D-dimer levels in the severe groups compared to the non-severe groups, regardless of the diabetic state." (PMID 35766706, 2022). "We compared six biochemical indices, including lactate dehydrogenase (LDH), platelet counts (PLT), neutrophilic granulocyte count (NEUT), white blood cell count (WBC), C-reactive protein (CRP), and LYM_N, among healthy, mild-type COVID-19, moderate-type COVID-19, and non-COVID-19 pneumonia groups." (PMID 35433742, 2022). "Patients without COVID-19 had higher CRP levels (24 vs 48 mg/L, p < 0.001)." (PMID 36376086, 2022). "Anti-ACE2 IgM–positive COVID-19 patients had higher levels of anti-S IgG than those without these antibodies, and patients with these IgMs had higher temperatures early after admission and higher CRP and D-dimer when severe disease became established." (PMID 35349483, 2022). "Moreover, a recent Mendelian randomization study showed a genetic correlation between COVID-19 and BMI but not CRP levels." (PMID 35013457, 2022). "In the course of patients’ hospitalization, the CRP and anti-S IgG levels were observed to, respectively, decrease and increase in COVID-19 patients; however, for none of these parameters the difference between the final and the initial level was correlated with patients’ age." (PMID 35495660, 2022). "In contrast, there was a moderate correlation of NP with CRP in non-COVID-19 but not in COVID-19." (PMID 35529699, 2022). "Meanwhile, patients without NAFLD and critical COVID-19 had higher serum concentrations of CRP (127 mg/L, IQR 75–202 vs. 89 mg/L, IQR 32–122; p = 0.016), procalcitonin (0.17 μg/L, IQR 0.11–0.28 vs. 0.09, IQR 0.06–0.12; p = 0.006), and LDH (511 IU/L, IQR 419–620 vs. 284, IQR 236–445; p = 0.012)." (PMID 35743825, 2022). "Consequently, this study showed evidence that serial WBC count, lymphocyte count, CRP, procalcitonin (PCT), LDH and AST measurements could be used as biomarkers for severe COVID-19." (PMID 35335635, 2022).
COVID-19 (continued). "13-year-old healthy girl who had COVID-19 3 weeks before, had presented to the general practitioner with fever and painful right sided neck swelling for 3 days and received oral clarythromycin treatment based on high WBC (11.5 × 103) and c-reactive protein [CRP] (76 mg/dL)." (PMID 36527007, 2022). "However, some tendency for a lower CRP, IL-6, PCT, and d-dimer, and a less frequent requirement for oxygen supplementation were noted in patients who received a booster at least 14 days prior to their first COVID-19 symptoms." (PMID 35455306, 2022). "Furthermore, sACE2 was positively correlated with platelets (r = 0.50, p = 0.01) in non-diabetic COVID-19 patients as well as CRP (r = 0.44, p = 0.024) and aPTT (r = 0.458, p = 0.021) in diabetic COVID-19 patients." (PMID 35455065, 2022). "Moreover, a prognosis was poor for patients with severe COVID-19 if they had a consistently high level or trend for an increase in neutrophil frequency and increased serum concentrations of IL-6, procalcitonin, D-dimer, SAA, and CRP during hospitalization." (PMID 35632823, 2022). "Importantly, CRP concentration was markedly higher in hospitalized vs. non-hospitalized post-COVID-19 patients." (PMID 36552357, 2022). "One study reported that CRP has recently been found to be a valuable marker for predicting the possibility of aggravation of non-severe adult COVID-19, with an optimal threshold value of 26.9 mg/L. Moreover, most of the admitted COVID-19 patients exhibited high lactic acid levels." (PMID 35774706, 2022). "While the compatible part with this study is leukocytosis, leukocytosis, and lymphopenia, differences in our study are the groups consisting of pregnant women with and without COVID-19, high CRP level in COVID-19 pregnant women, and low Neutrophil/Lymphocyte ratio." (PMID 36263236, 2022). "However, researchers recommend CRP as a monitoring and prognosis tool in patients diagnosed with both TB and COVID-19, rather than as a rule-out screening test." (PMID 36090970, 2022). "Upon analyzing these factors, we wanted to analyze if CRP alone and in combination with other factors could help to distinguish MIS-C (both with and without acute appendicitis) cases from acute appendicitis or acute appendicitis with COVID-19 in our data." (PMID 36013568, 2022). "To summarize, an increased level of CRP may be a useful early marker in predicting the probability of disease progression in non-severe individuals who have COVID-19." (PMID 36431254, 2022). "However, there is a limitation in interpretation of the correlation analysis in non-COVID-19 patients, because two non-COVID-19 patients showed extremely high CRP levels (71.9 and 82.5 mg/dl) affecting the correlation analysis." (PMID 35529699, 2022). "Compared to COVID-19 negative patients, those who are positive patients had significantly higher levels of C-reactive protein, D-dimer, and thrombus grade (p < 0.05) and showed more frequent use of thrombus aspiration and glycoprotein IIbIIIa (Gp2b3a) inhibitor (p < 0.05)." (PMID 35360030, 2022). "So that, the amount of sPD-L1 is increased in COVID-19 patients as compared to healthy controls, which is correlated with a lower number of lymphocytes and partial pressure of oxygen (PaO2) to the fraction of inspired oxygen (FIO2) (P/F) as well as a higher level of C reactive protein (CRP)." (PMID 36038915, 2022). "The examples of both atherogenesis and COVID-19 impressingly demonstrated that a component of ancient immunity like CRP should not be considered under identical “beneficial” auspices throughout phylogeny but might effect quite the reverse as well." (PMID 35402541, 2022). "Chemotherapy recipients were also those patients characterized by a statistically significantly lower median CRP and NLR, leading us to postulate whether the protective effect of chemotherapy on COVID-19 sequelae might be related to a therapy-dependent modulation of the proinflammatory response." (PMID 35417006, 2022).
COVID-19 (continued). "Herein, we discovered that age (≥60 years V < 60 years), dyspnea (yes V no), lymphocyte count (low V normal), CRP (high V normal) and IL-6 (high V normal) were independent factors to infer the severe disease occurrence out of common type of COVID-19, in which age was the most important contributor." (PMID 35037900, 2022). "Interestingly, CRP was increased by a 1.5x fold count in high severity participants versus low, but CRP for low severity participants was lower than for COVID-19 negative participants." (PMID 36137157, 2022). "Finally, COVID-19 worsening during hospitalization is also positively correlated with admission plasma levels of IL-8/CXCL8, MCP-1/CCL2, IL-10, and C-reactive protein." (PMID 36035415, 2022). "Zhou and colleagues, investigating the impacts of COVID-19 on cognitive functions in patients who recovered from the viral infection, found that there was a correlation of cognitive impairment, as measured by the continuous performance test (CPT), with levels of C-reactive protein." (PMID 35409141, 2022). "Elevated levels of CRP, ferritin, and IL-6 concentrations have been shown to be higher in cytokine storm disorders, patients with severe COVID-19, and in non-survivors of COVID-19 compared to discharged patients." (PMID 35303909, 2022). "Also, the higher values of the neutrophil count, CRP, D dimer, PCT, LDH, urea, creatinine, CK, Ferritin, TBIL, AST, as well as lower values of lymphocyte and monocyte count, and albumin were detected in the group of patients with severe COVID-19." (PMID 34917631, 2021). "COVID-19 malignant patients had significantly lower hemoglobin and platelets compared to COVID non-malignant ones, while they had significantly higher C-reactive protein, LDH, AST, Albunim, creatinine, and prognostic index (PI) compared to COVID-19 non-malignant patients." (PMID 33617530, 2021). "Compared to patients without HTN, hypertensive-COVID-19 patients were older, exhibited higher C-reactive protein (CRP), erythrocyte sedimentation rate, and comorbidities such as diabetes, coronary heart disease, cerebrovascular disease and chronic kidney disease." (PMID 34789776, 2021). "CRP is elevated in response to inflammation and the level can reflect a persistent state of inflammation which is not affected by factors such as age and gender, detected CRP levels in COVID-19 patients is of great value in assessing the severity of the disease." (PMID 34195215, 2021). "In patients with simultaneous ST-elevation ACS and COVID-19, systemic inflammatory response was significantly higher than in patients without COVID-19, including higher levels of D-dimer, troponin-T, fibrinogen, ferritin, and CRP, as well as lower lymphocyte counts." (PMID 34198968, 2021). "However, when looking at acute-phase proteins (APPs), the significant increase of C-reactive protein (CRP) and ferritin in COVID-19 patients (p < 0.001 and p < 0.001, respectively) could be observed." (PMID 34680053, 2021). "In the present meta-analysis, numerous inflammatory biomarkers (ESR, CRP, PCT, ferritin, and IL-6) were higher in deceased patients than in survivors, providing further evidence for the presence of a cytokine storm that can contribute to the fatal outcome of COVID-19 patients." (PMID 34238232, 2021). "However, early detection of high level of serum CRP, ALT/AST and ALP combined with a clinical COVID-19 symptom and finding of CT scan may be used as an index for the presence and severity of the disease." (PMID 34158795, 2021). "Furthermore, we found that, compared to females, males with COVID-19, although not significantly, had higher values of inflammatory markers such as C-reactive protein (CRP) and ESR." (PMID 33858472, 2021). "We found that the combination of five laboratory indicators, i.e., age, C-reactive protein, neutrophils, lymphocyte, and ferritin, can effectively predict whether the CT findings of COVID-19 children are positive or not." (PMID 34195215, 2021).
COVID-19 (continued). "However, higher CRP (P=0.0090) were found in male than in female severe COVID-19 patients, whereas these differences were non-significant between males and females in moderate COVID-19 patients, common viral CAP patients and healthy person." (PMID 33350432, 2021). "Many inflammatory stress molecules and pathways including Ang II-associated hypertensive stress, diabetes-related metabolic stress, cytokine storm, high CRP, overreactive TGF-β signaling, complement activation, and lung-kidney crosstalk may promote AKI in COVID-19 patients." (PMID 33907513, 2021). "Patients with COVID-19 had elevated D-dimer, thrombomodulin, and initial factor V elevation followed by decreased factor V and factor VII and elevated IL-6, lactate dehydrogenase, and c-reactive protein, which indicated coagulopathy and possible cytokine storm." (PMID 34829418, 2021). "Laboratory findings like chest X-ray, ESR, white blood cell (WBC) count, lymphocyte count, C-reactive protein (CRP), serum glutamic pyruvic transaminase (SGPT), serum ferritin, PT, D-dimer, and serum creatinine are important markers for the diagnosis and prognosis of COVID-19 illness (p < 0.05)." (PMID 34490284, 2021). "CRP was the single indicator that could best distinguish COVID-19 patients with or without clinical symptoms." (PMID 34722325, 2021). "Whilst CRP has been argued as an important marker of disease progression in COVID-19,6, its distribution has never been explored to understand whether distinct patterns exist in a heterogeneous population." (PMID 33683344, 2021). "Consistent with the literature, the significantly higher CRP, ferritin, PRC, D-dimer, and WBC values of the deceased patient group in our study indicate that inflammation and coagulation parameters are important prognostic parameters in severe COVID-19 patients." (PMID 34868686, 2021). "In line with this, serum levels of pro-inflammatory markers IL-6, C-reactive protein (CRP) and soluble IL2-receptor (sIL-2R) expression were higher and number of cytotoxic CD8+ T cells was lower in patients with severe/critical COVID-19 compared to mild COVID-19 of our study." (PMID 34869058, 2021). "There is no general agreement on a cut-off point of CRP to determine the severity of COVID-19." (PMID 33315349, 2021). "The relationship between CRP and depressed mood (model 6 OR = 1.70, 95% CI 1.38–2.09, p < 0.001), and fibrinogen and depressed mood (model 6 OR = 1.29, 95% CI 1.09–1.52, p = 0.003) was independent of these COVID-19 impact factors." (PMID 34887380, 2021). "In patients with COVID-19, the ROC analysis showed positive predictions of albumin and hematocrit, but negative predictions of C-reactive protein (CRP), procalcitonin (PCT), lactate dehydrogenase (LDH), hydroxybutyrate dehydrogenase (HBDH), and erythrocyte sedimentation rate." (PMID 34859002, 2021). "It is in fact known that a number of laboratory parameters are altered in COVID-19 patients and that some of these alterations, such as the decrease in lymphocyte count and increase in LDH, D-dimer, CRP could be considered predictors of adverse clinical outcomes." (PMID 33556140, 2021). "Though a recent meta-analysis have highlighted the prognostic value of increased CRP and D-dimer plasma levels in non-severe and severe COVID-19, the value of such markers in ICU settings is flawed, given that they are frequently increased, as we observed in our patients." (PMID 33924475, 2021). "Lymphocytopenia, thrombocytopenia, leukopenia, high levels of CRP, alanine transaminase (ALT), aspartate aminotransferase (AST), creatine phosphokinase (CPK), and D-dimer are among the laboratory findings that have been recorded among the majority of the COVID-19 clinical studies." (PMID 34084685, 2021). "An elevated level of CRP may be a valuable early marker in predicting the progression in non-severe patients with COVID-19." (PMID 35076497, 2021).